FDX1 (ferredoxin 1)
Diseases named in the same sentence as FDX1 in open-access papers (continued):
Sharing a sentence is not in itself a finding about the gene and the disease.
COVID-19 (3 papers, 2023 to 2024). A disease caused by infection with severe acute respiratory syndrome coronavirus 2. "According to a report, in COVID-19, ROS rises, so 13 CRGs’ change causes copper ion level’s imbalance in COVID-19 patients, which induces cuprotosis, and further regulates oxidative stress through FDX1-LIAS axis, leading to ROS’s rise in the body." (PMID 38581529, 2024). "It is reported that the ROS in patients with COVID-19 increases, so the level of copper ions in patients with COVID-19 is unbalanced, thus inducing cuprotosis, and further regulating oxidative stress through the FDX1-LAS axis, leading to the increase of ROS in the body." (PMID 39008196, 2024). "Therefore, SNCA may regulate the copper death pathway of patients with COVID-19, and further regulate oxidative stress through the FDX1-LAS axis, leading to the change of ROS in patients with COVID-19." (PMID 39008196, 2024). "The strong relations between neutrophils and CRGs and their strongest positive and negative correlations with MTF1 and FDX1, respectively, imply that MTF1 and FDX1 may regulate neutrophil infiltration in COVID-19." (PMID 37533853, 2023).
esophageal carcinoma (3 papers, 2022 to 2023). A primary or metastatic malignant neoplasm involving the esophagus. "FDX1 expression correlated negatively with that of TET2 and DNMT1 in BRCA, esophageal carcinoma (ESCA), GBM, HNSC, LIHC, LUAD, LUSC, and PCPG and correlated positively in skin cutaneous melanoma (SKCM)." (PMID 36210836, 2022).
lymph node metastasis (3 papers, 2022 to 2026). "FDX1 expression was significantly associated with tumor diameter, lymph node metastasis and distant metastasis (p < 0.05)." (PMID 38520567, 2025). "Univariate analysis showed that age, pathological grade, TNM stage, T classification, lymph node metastasis, distant metastasis, and FDX1 expression were important predictors of survival." (PMID 36105937, 2022). "The chi-square test showed that the high expression of FDX1 was related to gender, TNM stage, T stage, lymph node metastasis, and pathological grade." (PMID 36105937, 2022). "Additionally, the FDX1 expression level was different in groups classified based on pathological grade, gender, TNM stage, T stage, lymph node metastasis, and distant metastasis (P < 0.05)." (PMID 36105937, 2022). "In addition, the expression level of FDX1 was different in groups classified according to pathological grade, gender, TNM stage, T stage, lymph node metastasis, and distant metastasis (P < 0.05)." (PMID 36105937, 2022).
mesothelioma (3 papers, 2022). A usually malignant and aggressive neoplasm of the mesothelium which is often associated with exposure to asbestos. "Regarding PFS, a high expression of FDX1 was associated with poor PFS in LGG (HR = 2.74, p = 0.001) and ACC (HR = 1.34, p = 0.005), while a high expression of FDX1 could predict favorable PFS in mesothelioma (MESO) (HR = 0.54, p = 0.028), KIRC (HR = 0.49, p = 0.001), and THCA (HR = 0.46, p = 0.001)." (PMID 36605188, 2022).
non-small cell lung carcinoma (3 papers, 2022 to 2025). A group of at least three distinct histological types of lung cancer, including non-small cell squamous cell carcinoma, adenocarcinoma, and large cell carcinoma. "Our experimental results demonstrated that FDX1 exerts its antitumor effects through cuproptosis in liver hepatocellular carcinoma and non-small cell lung cancer cell lines." (PMID 36226187, 2022). "Finally, we validated the function of FDX1 in liver hepatocellular carcinoma and non-small cell lung cancer cell lines." (PMID 36226187, 2022). "In non-small cell lung cancer, METTL3 may promote the development of the disease by facilitating the maturation of pri-miR-21-5p, upregulating miR-21-5p, and targeting the inhibition of FDX1." (PMID 40276654, 2025).
steatosis (3 papers, 2023 to 2024). Increased lipid within the cytoplasm of cells. "FDX1 also acts as a key regulator of steatosis by directly binding to LIAS, thereby exerting a lethal metabolic effect on cancer cells." (PMID 39360273, 2024). "As steatohepatitis often leads to liver cirrhosis and eventually liver failure, we conclude that the high incidence of steatosis/steatohepatitis are likely responsible for the shorter lifespan observed in Fdx1+/- +/-." (PMID 38251655, 2024). "FDX1 was widely expressed around hepatocyte steatosis, as shown in the IHC results; this result was consistent in both the mouse NASH samples and human NASH samples." (PMID 37763758, 2023).
brain cancer (2 papers, 2022). A primary or metastatic malignant neoplasm affecting the brain. "Brain cancers (GBM and LGG) were found to potentially have a higher copper metabolism-related cell death compared to normal brain tissue because their anti-cuproptosis gene ATP7B was downregulated with pro-cuproptosis genes SLC31A1, FDX1, DLAT, and LIAS upregulated in cancer tissues." (PMID 36276096, 2022).
cardiomyopathy (2 papers, 2023 to 2025). A disease of the heart muscle or myocardium proper. "In the future, the SLC31A1 gene and FDX1 gene are expected to be potential therapeutic targets for primary cardiomyopathy." (PMID 38085668, 2023). "Previous studies have never reported the role of FDX1 in cardiomyopathy or heart failure." (PMID 38085668, 2023).
coronary artery disease (2 papers, 2023 to 2024). "Indeed, genome-wide association studies identified FDX1 as a susceptibility loci in the coronary artery disease." (PMID 37442861, 2023).
diffuse large B-cell lymphoma (2 papers, 2022 to 2023). "However, a large majority of cuproptosis-associated genes including FDX1, LIAS, LIPT1, DLD, DLAT, and PDHB acted as a low-risk indicator in Lymphoid neoplasm diffuse large B-cell lymphoma (DLBC)." (PMID 36105090, 2022).
gastric tumors (2 papers, 2023 to 2024). "In gastric tumors, RNA methyltransferase METTL16 could promote cuproptosis by facilitating FDX1 accumulation through m6A modification on FDX1 mRNA." (PMID 38918694, 2024).
heart failure (2 papers, 2023 to 2024). Inability of the heart to pump blood at an adequate rate to meet tissue metabolic requirements. "This raises the possibility of compensatory regulatory mechanisms within the body that protect cells from copper toxicity by downregulating FDX1 expression during the prolonged progression of heart failure post‐ischemic events." (PMID 38509725, 2024).
liver fibrosis (2 papers, 2025). "The dynamic changes in FDX1 and LIAS reflect the adaptive response and regulatory mechanisms of HSCs when faced with DATs treatment, providing new insights into the application of copper death in the treatment of liver fibrosis." (PMID 40213908, 2025).
Obesity (2 papers, 2022 to 2024). Accumulation of substantial excess body fat. "The FDX1/ARHGAP20 locus has been associated with renal sinus fat which has a proposed link between obesity and renal function." (PMID 35115544, 2022). "We observed significant upregulation of genes such as Cyp11a1, Fdx1, Flt1, Gm2a, and S100a6 in the G05 subpopulation under the influence of obesity." (PMID 38956667, 2024).
osteoarthritis (2 papers, 2024). A noninflammatory degenerative joint disease occurring chiefly in older persons, characterized by degeneration of the articular cartilage, hypertrophy of bone at the margins and changes in the synovial membrane. "Additionally, five genes related to cuproptosis (FDX1, LIPT1, PDHA1, PDHB, and CDKN2A) are considered candidate biomarkers or therapeutic targets for osteoarthritis synovitis." (PMID 39360273, 2024).
ovarian serous cystadenocarcinoma (2 papers, 2022 to 2023). A malignant serous cystic epithelial neoplasm arising from the ovary. "Likewise, FDX1 expression was positively correlated with NSUN6 levels in 10 tumors, except for GBM, KIRC, KIRP, brain lower grade glioma (LGG), and ovarian serous cystadenocarcinoma (OV)." (PMID 36210836, 2022).
periodontitis (2 papers, 2023 to 2024). An acute or chronic inflammatory process that affects the tissues that surround and support the teeth. "Notably, genes associated with cuproptosis, including Fdx1, Lias, Dld, and Dlat, were expressed in periodontitis tissue." (PMID 38892077, 2024).
pulmonary fibrosis (2 papers, 2022 to 2023). Chronic progressive interstitial lung disorder characterized by the replacement of the lung tissue by connective tissue, leading to progressive dyspnea, respiratory failure, or right heart failure. "In the mouse model of pulmonary fibrosis induced by bleomycin, the genes related to cuproptosis promotion, such as Fdx1, Lias, Dld, Pdha1, Pdhb, Dlat, and Lipt1, were gradually down-regulated in the process of fibroblast differentiation from resting fibroblast to myofibroblast." (PMID 36601107, 2022). "It’s reported that the CRGs, such as FDX1, LIAS, DLD, PDHA1, PDHB, DLAT, and LIPT1, were down-regulated in the lung tissues of pulmonary fibrosis mouse model, and the same results were obtained via analysis of lung tissues scRNA-seq data for human pulmonary fibrosis." (PMID 37266442, 2023).
Sepsis (2 papers, 2025). Sepsis is defined as life-threatening organ dysfunction caused by a dysregulated host response to infection. "The expression of SLC31A1, CD274, ATOX1, MTF1, UBE2D1, DLD, and VEGFA was found to be upregulated, while that of DLST, UBE2D2, COX11, DLAT, GLS, FDX1, and ULK2 were significantly downregulated in patients with sepsis-associated ALI." (PMID 38779731, 2025). "HKDC1 interacts with heat shock cognate B (HSCB) and ferredoxin 1 (FDX1), leading to increased intracellular copper levels and subsequent cuproptosis.HKDC1 knockdownin vivo alleviates acute sepsis by activating copper-dependent cell death pathways." (PMID 40692442, 2025).
TCA cycle disorders (2 papers, 2024 to 2025). "We observed that knockdown of FDX1, which is known to cause TCA cycle disorders in cuproptosis, reversed the elesclomol-induced increase in PPP1R15A expression." (PMID 38365764, 2024).
acute kidney injury (1 paper, 2025). Sudden and sustained deterioration of the kidney function characterized by decreased glomerular filtration rate, increased serum creatinine or oliguria. "Furthermore, research has linked CP-induced acute kidney injury (AKI) cuproptosis through the FDX1-DLAT axis, alongside upregulation of Cu transporters." (PMID 41301513, 2025).
adrenal cancer (1 paper, 2022). A carcinoma involving a adrenal gland. "Across cancer cell lines, neuroblastoma displayed the lowest FDX1 mRNA expression level in the box plot; adrenal cancer had the highest expression." (PMID 36186457, 2022).
Adrenal insufficiency (1 paper, 2025). Insufficient production of steroid hormones (primarily cortisol) by the adrenal glands. "Mutations in FDX1, which does participate in steroidogenesis have not (yet) been reported, but we predict that they will be found and will cause adrenal insufficiency." (PMID 39574227, 2025).
Ataxia (1 paper, 2020). Ataxia refers to impaired coordination of voluntary muscle movement. "The surprising number of patient families with FDXR mutations that have been discovered in such a short period of time raises the possibility that the FDXR/FDX1/FDX2 pathway may lie behind many cases of optic atrophy and ataxia with no previously identified cause." (PMID 32499495, 2020).
biliary atresia (1 paper, 2026). A rare, biliary tract disease characterized by progressive obliterative cholangiopathy of the intra- and extrahepatic bile ducts, occurring in the embryonic/ perinatal period, leading to severe and persistent neonatal jaundice and acholic stool. "Single-cell sequencing of biliary atresia (BA) patients’ cholestatic liver specimens demonstrated downregulation of FDX1, a key cuproptosis marker, in BA hepatocytes." (PMID 41513631, 2026).
breast tumor (1 paper, 2022). "Normal breast and lung tissues, and lung and breast tumor tissues did not detect with FDX1 staining." (PMID 36210836, 2022).
calcification (1 paper, 2025). Process by which organic tissue becomes hardened by the physiologic deposit of calcium salts. "Notably, inhibition of cuproptosis through Elabela-mediated activation of the PPAR-γ/FDX1 signaling axis has been shown to protect against arterial calcification." (PMID 41463296, 2025).
cholestasis (1 paper, 2026). Impairment of the bile flow caused by obstruction within the liver, or outside the liver in the bile duct system. "Cholestasis-induced copper overload drives liver injury via taurocholic acid-exacerbated and FDX1-mediated cuproptosis." (PMID 41513631, 2026).
Cholestatic liver disease (1 paper, 2026). "As reported in multiple studies, FDX1 was down-regulated after copper intervention, while the exact regulatory effect on copper-induced cell death in cholestatic liver disease remains to be explored." (PMID 41513631, 2026).
embryonal carcinoma (1 paper, 2025). A non-seminomatous malignant germ cell tumor characterized by the presence of large germ cells with abundant cytoplasm resembling epithelial cells, geographic necrosis, high mitotic activity, and pseudoglandular and pseudopapillary structures formation. "Expression of genes involved in general steroid biosynthesis (STAR, POMC, CYP11A1, FDX1) and the aromatase-coding gene CYP19A1 was the highest in embryonal carcinomas." (PMID 40011822, 2025).
endometriosis (1 paper, 2024). The growth of functional endometrial tissue in anatomic sites outside the uterine body. "According to a recent study, FDX1 mediates cuproptosis in endometriosis through the G6PD pathway, which inhibits the proliferation and metastasis of endometriosis cells." (PMID 38397379, 2024).
Fever (1 paper, 2025). Body temperature elevated above the normal range. "After taking the intersection of the DEGs with the 10 FRGs, we obtained 3 fever-related DEGs, and the expression level of FDX1 was significantly higher in the fever group." (PMID 40430430, 2025).
fibrosarcoma (1 paper, 2024). A malignant mesenchymal fibroblastic neoplasm affecting the soft tissue and bone. "These demonstrated that the FDX1 protein levels were associated with the immune microenvironment in fibrosarcoma." (PMID 38938647, 2024). "First of all, to investigate the correlation of FDX1 with the immune microenvironment in fibrosarcoma, we analyzed the expression of FDX1 in normal and tumor tissue." (PMID 38938647, 2024). "FDX1 expression was found to be positively correlated with the percentage of CD8+ T cells and CD4+ T cells in fibrosarcoma." (PMID 38938647, 2024). "The results also revealed that FDX1 was significantly positively correlated with expression of costimulatory molecules CD80 and CD86 in fibrosarcoma." (PMID 38938647, 2024).
hepatitis B (1 paper, 2023). "FDX1 expression in patients with LIHC with risk factors (alcohol consumption, hepatitis B, or hepatitis C) and in the no-risk factor group was no different, although there was a significant difference between patients with no-risk factor, alcohol consumption, or Hepatitis B and the complex group." (PMID 37361595, 2023).
infertile (1 paper, 2025). "Future studies should explore urinary/serum copper levels and FDX1 activity in infertile males, potentially establishing FDX1 as a diagnostic biomarker or therapeutic target." (PMID 40331931, 2025).
ischemia (1 paper, 2024). A hypoperfusion of the BLOOD through an organ or tissue caused by a PATHOLOGIC CONSTRICTION or obstruction of its BLOOD VESSELS, or an absence of BLOOD CIRCULATION. "Finally, FDX1 expression was significantly upregulated in the hippocampus of ovariectomized rats with ischemia." (PMID 39360273, 2024).
liposarcoma (1 paper, 2022). A usually painless malignant tumor that arises from adipose tissue. "The downregulation of DLAT has been associated with its chromosomal deletions in liposarcoma, thus suggesting that the chromosomal deletions of FDX1 and DLAT may affect their own expression levels." (PMID 36685880, 2022).
Miscarriage (1 paper, 2024). A pregnancy that ends at a stage in which the fetus is incapable of surviving on its own, defined as the spontaneous loss of a fetus before the 22th week of pregnancy. "Thus, Fdx1-/- embryos would not be able to survive due to a miscarriage." (PMID 38251655, 2024).
motor neuron degeneration (1 paper, 2025). "SLC25A20 and FDX1 emphasized mitochondrial lipid biosynthesis and catabolism, while COA3 linked to mitochondrial genetic information processing and protein translation, suggesting broader biogenesis defects in motor neuron degeneration." (PMID 40864790, 2025).
postmenopausal osteoporosis (1 paper, 2026). Metabolic disorder associated with fractures of the femoral neck, vertebrae, and distal forearm. "Our findings suggest that the novel Estrogen/SIRT5/FDX1 axis may function as a key regulator of bone homeostasis, and identify SIRT5 as a potential therapeutic candidate for postmenopausal osteoporosis, likely through its capacity to reduce the cuproptosis-like features of mesenchymal stem cells." (PMID 42290657, 2026).
primary cardiomyopathy (1 paper, 2023). "Our study is the first to find that FDX1 is significantly down-regulated in three kinds of primary cardiomyopathy, suggesting that FDX1 may be involved in the pathogenesis of primary cardiomyopathy through cuproptosis mechanism." (PMID 38085668, 2023). "Therefore, we ultimately identified four genes as differential CRGs shared by the three kinds of primary cardiomyopathy: COA6, FDX1, MAP2K1, and SLC31A1." (PMID 38085668, 2023). "The mRNA and protein levels of FDX1, MAP2K1 and SLC31A1 were significantly down-regulated during cuproptosis in cardiomyocytes, which was in line with the expression trends of the three kinds of primary cardiomyopathy groups in the GEO datasets." (PMID 38085668, 2023). "These four CRGs contained two core genes (FDX1 and SLC31A1) that regulate cuproptosis, suggesting that cuproptosis may be the common pathogenesis of the three kinds of primary cardiomyopathy." (PMID 38085668, 2023).
rhabdomyosarcoma (1 paper, 2022). A rare aggressive malignant mesenchymal neoplasm arising from skeletal muscle. "However, we reached the opposite result to a previous study, in which elesclomol could directly target FDX1 and promote copper-induced cell death in human rhabdomyosarcoma and LUAD cells." (PMID 36210836, 2022).
synovitis (1 paper, 2023). Inflammation of a synovial membrane. "In our research, the downregulation of DBT and DLST, together with the upregulation of FDX1 and LIPT1, may indicate the potential role of cuproptosis in OA synovitis." (PMID 36671512, 2023).